NLRP3 (NLR family pyrin domain containing 3)
Diseases named in the same sentence as NLRP3 in open-access papers (continued):
Sharing a sentence is not in itself a finding about the gene and the disease.
atherosclerosis (continued). "NLRP3 inflammasome hyperactivation plays crucial roles in various inflammatory diseases, including arthritis, systemic lupus erythematosus, asthma, and atherosclerosis." (PMID 41463800, 2025). "Collectively, these findings demonstrated that PEMFs mitigate atherosclerosis by reversing mitochondrial structural and functional deficits (including impaired respiration), thereby inhibiting NLRP3 inflammasome activation and endothelial pyroptosis." (PMID 41309549, 2025). "Evodiamine and rutaecarpine inhibit several inflammatory diseases, including gouty arthritis, colitis, and atherosclerosis, through suppressing NLRP3 inflammasome activation." (PMID 38708084, 2024). "In late-stage atherosclerosis, NLRP3 inflammasomes induce macrophage cell death by pyroptosis, releasing IL-1β, IL-18, and inflammatory lipids, which increase plaque size and vulnerability to vessel rupture." (PMID 38335214, 2024). "Studies have shown that the NLRP3 inflammasome is activated in cholesterol overload states and plays a direct role in promoting atherosclerosis." (PMID 38705278, 2024). "IKKε knockdown not only significantly attenuated atherosclerosis lesions of aortic arch areas in ApoE−/− mice fed with high cholesterol diets, but also markedly reduced endothelial cell pyroptosis and NLRP3 expression triggered by low-shear stress." (PMID 38315275, 2024). "Studying the relationship between the NLRP3 inflammasome and gut microbiota in atherosclerosis is vital for progress in preventing and treating this disease." (PMID 39092226, 2024). "In conjunction with TLR4, Olfr2 expressed in mouse vascular macrophages can active NLRP3 inflammasome to promote the development of atherosclerosis." (PMID 38803504, 2024). "Among the most widely studied in the context of atherosclerosis is the cytosolic multiprotein signaling complex called the NLRP3 inflammasome, which serves as a platform for the activation of caspase-1 and promotes the synthesis of pro-inflammatory cytokines." (PMID 39055657, 2024). "NLRP3, which is the best-characterised inflammasome, is upregulated in cardiovascular disorders including atherosclerosis, myocardial infarction, ischemic heart disease, chronic heart failure and hypertension." (PMID 39769058, 2024). "The NLRP3 inflammasome, a key driver of inflammation in atherosclerosis, can be activated through three main mechanisms." (PMID 39022620, 2024). "In vivo studies have indicated its application for multiple NLRP3-driven diseases, such as type 2 diabetes, atherosclerosis, CNS disorders such as Alzheimer’s and Parkinson’s disease, inflammation and cancer." (PMID 38945951, 2024). "Targeted inhibition of the NLRP3 inflammasome pathway represents another ongoing promising approach to slow atherosclerosis." (PMID 38275616, 2024). "The NLRP3 inflammasome is required for atherosclerosis, and the by‐products of pyroptosis, IL‐1β and IL‐18, contribute to the occurrence and development of plaques." (PMID 38873710, 2024). "According to previous findings, Corilagin can inhibit NLRP3 inflammasome activation and pyroptosis in ischemia-reperfusion induced intestinal and lung injury, and ameliorate atherosclerosis by restraining the TLR4 signaling pathway." (PMID 38803504, 2024). "It has also been shown that dietary PUFAs, including DHA, can detect and attenuate NLRP3 inflammasome activation in human macrophages primed with LPS, and attenuate atherosclerosis development in a mouse model via inhibition of NLRP3 inflammasome activation." (PMID 39125448, 2024). "Growing evidence suggests that the activation of NLRP3 inflammasome is significantly involved in the pathophysiology of cardiovascular diseases, including atherosclerosis and acute MI." (PMID 38911926, 2024). "In our prior investigation, we demonstrated that GP73 promotes atherosclerosis by activating NF-κB/NLRP3 inflammasome signaling." (PMID 39239555, 2024).
atherosclerosis (continued). "In our experiments that modulated Olfr2 expression both in vitro and in vivo, we observed analogous outcomes confirming that the Olfr2 signaling pathway indeed activated the NLRP3 inflammasome, exacerbating atherosclerosis development and progression." (PMID 38803504, 2024). "CTSB is intimately associated with metabolic disorders such as type 2 diabetes, atherosclerosis, cardiac reperfusion injury, and chronic kidney disease through regulating the NLRP3 inflammasome in the cytoplasm." (PMID 39716081, 2024). "LncRNA MALAT1 was found to regulate the expression of NLRP3, and upregulation of MALAT1 exacerbated NLRP3-mediated cellular pyroptosis in diabetic rat atherosclerosis." (PMID 38439031, 2024). "The adverse impact of NLRP3 on atherosclerosis primarily hinges on the action of its downstream cytokine IL-1β." (PMID 38248345, 2024). "NLRP3 probably has a role in the pathogenesis of atherosclerosis, acting as a proinflammatory molecule that triggers the activation of caspase-1 and pro-IL-1β, pro-IL-18, and the initiation of pyroptosis." (PMID 38929699, 2024). "One study demonstrated that nicotine promotes NLRP3 inflammasome activation in peripheral myeloid cells, driving atherosclerosis progression due to inflammatory cytokine release in macrophages and monocytes." (PMID 39529883, 2024). "Among these inflammasomes, the NLR family pyrin domain containing 3 (NLRP3) inflammasome is the most crucial type involved in innate inflammation in atherosclerosis because it is highly expressed in monocytes and macrophages." (PMID 39392102, 2024). "Nonetheless, the specific impact of Corilagin on NLRP3 inflammasome activation in atherosclerosis necessitates further investigation." (PMID 38803504, 2024). "Numerous previous studies have shown that inflammation in AAA and atherosclerosis is mainly mediated by the NLRP3 inflammasome." (PMID 38732221, 2024). "The green cluster is primarily related to inflammatory diseases (atherosclerosis, insulin resistance, steatohepatitis, and obesity), gut microbiota, fat metabolism, and the NLRP3 inflammasome." (PMID 39834371, 2024). "The presence of NLRP3 indicates inflammation and initiation of atherosclerosis in patients with SLE." (PMID 39686502, 2024). "Some reports have suggested that P2X7 receptor or hypoxia-mediated K+ efflux and mtROS/mtDNA production contribute to NLRP3 activation, and the subsequent release of active IL-1β induces vascular inflammation and ultimately leads to atherosclerosis." (PMID 38732221, 2024). "For instance, a small molecule drug (MCC950) that selectively targets NLRP3 inflammatory vesicles can effectively block its activation, thereby significantly delaying the progression of atherosclerosis." (PMID 39022620, 2024). "A recent study on Apoe−/− mice revealed that oxLDL triggered the upregulation of TRIM64 expression, the activation of NF-κB signaling and NLRP3 inflammasome in macrophages, ultimately resulting in plaque inflammation and the development of atherosclerosis." (PMID 39528464, 2024). "In contrast to TET2 and DNMT3A, where NLRP3 inflammasome activation appears predominant as a mechanism that drives accelerated atherosclerosis, recent data suggest that ASXL1 and JAK2 CHIP provoke activation of the AIM2 inflammasome." (PMID 39352379, 2024). "Animal experiments in a diabetic atherosclerosis mouse model showed that knockdown of NLRP3 inhibited the expression of intima-media adhesion molecules, reduced atherosclerosis, and stabilized atherosclerotic plaques." (PMID 38439031, 2024). "The NLR family pyrin domain–containing 3 (NLRP3) inflammasome is often nominated as another anti-inflammatory target in atherosclerosis." (PMID 38705278, 2024).
atherosclerosis (continued). "The activation of the NLRP3 inflammasome contributes to endothelial dysfunction and hypertension, vascular inflammation, and atherosclerosis, thereby promoting the development and progression of cardiovascular diseases." (PMID 39594530, 2024). "Several studies depicted that EVs, in particular exosomes, are involved in the release of inflammasomes and its products, such as NLRP3 and IL-1β in mammalian cells, which enhanced progression of atherosclerosis." (PMID 39770410, 2024). "In mice, macrophage NLRP3 inflammasome activation worsens atherosclerosis, especially when hypercholesterolemia is accompanied by additional pro-inflammatory processes such as diabetes, clonal hematopoiesis (CH), or defective cholesterol efflux." (PMID 38522750, 2024). "The targeted downregulation of the NLRP3 inflammasome has been advocated across studies to attenuate atherosclerosis onset." (PMID 39337693, 2024). "In myeloid cells, NLRP3 activation and inflammatory cytokine release are associated with many HIV-associated inflammatory processes, such as atherosclerosis." (PMID 39529883, 2024). "Inflammasome Nod-Like Receptor Protein 3 (NLRP3) is an important component of innate immunity, known to be involved in the pathogenesis of atherosclerosis, metabolic syndrome, diabetes, obesity, and inflammatory and autoimmune diseases." (PMID 38929699, 2024). "The endoplasmic reticulum (ER), a crucial organelle responsible for regulating fundamental cellular processes, contains stress signalling pathways that have been shown to affect NLRP3 inflammasome activation and contribute to atherosclerosis." (PMID 39769058, 2024). "The NLRP3 inflammasome aggravates atherosclerosis; however, cellular mechanisms connecting macrophage cholesterol accumulation to inflammasome activation are poorly understood." (PMID 38522750, 2024). "There is a well-established relationship between nicotine and NLRP3-driven atherosclerosis progression." (PMID 39529883, 2024). "The abnormal activation of the NLRP3 inflammasome has been connected to several inflammatory diseases, such as Alzheimer’s disease, diabetes, and atherosclerosis." (PMID 38419883, 2024). "For example, NLRP3 inhibitor MCC950 has the potential to prevent NLRP3-related diseases, such as cardiac hypertrophy, hypertension, atherosclerosis, and myocardial injury." (PMID 39403576, 2024). "Mounting evidence has indicated that NLRP3 inflammasome activation is vital for the development of diabetes‐related atherosclerosis." (PMID 38774996, 2024). "Purinergic signaling in NLRP3-inflammasome activation plays an important role in a variety of inflammatory diseases such as atherosclerosis, diabetes or other inflammatory disorders." (PMID 37410223, 2024). "Recent research has identified that the olfactory receptor 2 (Olfr2) in vascular macrophages is instrumental in driving atherosclerosis through NLRP3- dependent IL-1 production." (PMID 38803504, 2024). "Increased macrophage cholesterol content, because of the deletion of cholesterol efflux-promoting transporters Abca1 and Abcg1, leads to increased NLRP3 inflammasome activation which promotes atherosclerosis." (PMID 38522750, 2024). "CMA function becomes impaired in atherosclerosis progression, leading to NLRP3 inflammasome activation and IL-1β secretion and promoting vascular inflammation and atherosclerosis progression." (PMID 39119608, 2024). "Among cellular responses modulated by MAPK signaling, the activation of NLRP3 inflammasome has been the focus of recent research, since its role in the onset and progression of atherosclerosis has been highlighted." (PMID 38706564, 2024).
atherosclerosis (continued). "The NLRP3 inflammasome acts as a sensor to deleterious exogenous and endogenous entities to activate pro-inflammatory signaling and culminate in CVDs viz atherosclerosis." (PMID 39337693, 2024). "In particular, the levels of NLRP3 inflammasome components such as Caspase-1, IL-1β, and IL-18 are increased in coronary atherosclerotic lesions, suggesting that NLRP3 plays an important role in the occurrence and development of atherosclerosis." (PMID 39092226, 2024). "In brief, our data reveal that LSS-induced IKKε phosphorylation activates the downstream transcription factor STAT1 and upregulates NLRP3 expression, ultimately triggering endothelial pyroptosis and atherosclerosis progression." (PMID 38315275, 2024). "In animal models, NLRP3 deletion has proven to be a significant preventive measure against atherosclerosis and lesion development." (PMID 39301197, 2024). "Recent research has emphatically highlighted the critical role of the NLRP3 inflammasome in the progression of atherosclerosis." (PMID 38803664, 2024). "Cholesterol crystals, triggered by metabolic imbalance and high intake of certain fats, activate NLRP3 in peripheral blood mononuclear cells (PBMNCs), a process crucial in atherosclerosis development." (PMID 39301197, 2024). "In both transplantation models, neutrophilia and atherosclerosis were consistently abolished in the alternating HFD group a finding recapitulated in mice receiving the NLR family pyrin domain containing 3 (NLRP3) inflammasome inhibitor MCC950." (PMID 39511153, 2024). "In early-stage atherosclerosis, monocytes/macrophages recognize and internalize oxLDL; NLRP3 inflammasomes are activated and macrophages differentiate into foam cells." (PMID 38335214, 2024). "CMA function becomes impaired during atherosclerosis progression, leading to increases in NLRP3 inflammasome activation and IL-1β secretion, boosting vascular inflammation and atherosclerosis progression." (PMID 39119608, 2024). "TET2 LOF appears to promote atherosclerosis primarily via enhanced transcription and NLRP3-mediated posttranslational processing of the inflammatory cytokine IL-1β." (PMID 39352379, 2024). "For example, a study found that two ferroptosis-related proteins, PTGS2 and ACSL4, and two necroptosis-related proteins, NLRP3 and caspase-1, are upregulated in the advanced stages of atherosclerosis (AS) and are positively correlated with the severity of AS." (PMID 39072329, 2024). "Activated NLRP3 inflammasomes within macrophages participate in the pathogenesis of atherosclerosis by increasing formation of foam cells." (PMID 38335214, 2024). "Some molecules proved to be good targets for inhibiting NLRP3, such as MCC950, with a marked reduction of the atherosclerotic lesions in ApoE-deficient mouse model and future promising perspectives for atherosclerosis." (PMID 37600028, 2023). "In preclinical studies, the direct function of NLRP3 on atherosclerosis pathology has been explored." (PMID 37336361, 2023). "NLRP3 inflammasome is involved in the inflammatory process to develop atherosclerosis and coronary atherosclerotic plaque formation and destabilization." (PMID 36988260, 2023). "In particular, NLR family pyrin domain containing 3 (NLRP3) is important in the mediation of periodontalinfection in atherosclerosis, for example, it was seen that after periodontaltreatment, NLRP3 was significantly reduced in gingival tissues." (PMID 39077574, 2023). "SGLT2 inhibitors were suggested to ameliorate atherosclerosis and cognitive dysfunction by inhibiting the NLRP3 inflammasome." (PMID 37242177, 2023). "These authors also provide evidence consistent with ox-mtDNA driving NLRP3-dependent inflammation in mouse models of atherosclerosis." (PMID 37001140, 2023). "miR-145 and miR-155 target the NLRP3 inflammasome by regulating upstream pathways of chronic inflammation in the context of atherosclerosis." (PMID 37498354, 2023).
atherosclerosis (continued). "In this review, we summarize the current findings related to the interactions between PCSK9 and the NLRP3 inflammasome in atherosclerosis." (PMID 36911736, 2023). "In the LAMP‐2A knockout mouse model, NLRP3 activation was enhanced, and atherosclerosis in the aorta was accelerated." (PMID 37655052, 2023). "In contrast to IR and AT inflammation, the activational triggers of the NLRP3 inflammasome in atherosclerosis are well defined and crystallized oxidated LDL (oxLDL) has been identified as one of the main activators in atherosclerotic lesions." (PMID 37239938, 2023). "Decreasing NLRP3 inflammasome activity is able to ameliorate many diseases, including gout, atherosclerosis, Alzheimer disease, traumatic brain injury and stroke." (PMID 37047097, 2023). "Despite studies confirming that ALDH2 can negatively regulate NLRP3 inflammasome and delay the development of atherosclerosis, the mechanisms involved are still poorly understood." (PMID 36910525, 2023). "Altogether, a large body of evidence demonstrates that the NLRP3 inflammasome contributes significantly to the development and progression of obesity-associated comorbidities such as IR, T2DM, atherosclerosis and NAFLD." (PMID 37239938, 2023). "NLRP3-mediated pyroptosis in PASMCs is found to be involved in the occurrence and development of atherosclerosis and pulmonary hypertension." (PMID 37828459, 2023). "NLRP3 inflammasome has also been shown to be regulated by PI3K/Akt signaling in atherosclerosis and inhibitors of PI3K (GDC0941) and Akt (MK2206) significantly reduced the activation of NLRP3 and expression levels of p-p65/p65." (PMID 37325475, 2023). "For instance, macrophages and foam cells pyroptosis mediated by NLRP3 contribute to the advancement of atherosclerosis." (PMID 36229750, 2023). "Low-grade basal NLRP3 inflammasome activation promotes the development of various chronic cardiovascular diseases such as hypertension and atherosclerosis." (PMID 37370025, 2023). "Targeting the TXNIP/NLRP3-mediated pyroptotic pathway in macrophages can ameliorate nicotine-induced endothelial injury and atherosclerosis." (PMID 36873396, 2023). "Dynamin-related protein 1 (mdivi-1), a Drp1 specific inhibitor, alleviates atherosclerosis in ApoE−/− mice by suppressing mito-ROS/NLRP3-mediated M1 polarization." (PMID 38031118, 2023). "The NLRP3 protein is involved in a variety of inflammatory pathologies, including neurological and autoimmune disorders, lung diseases, atherosclerosis, myocardial infarction, and many others." (PMID 36677800, 2023). "Inflammatory macrophage cluster identified from an atherosclerosis mouse model showed high-level expression of various genes previously assigned to a pro-atherogenic role (e.g., Ccl3, Il1b, Il1a, Nlrp3, Cebpb, Egr1, and Phlda1)." (PMID 38149246, 2023). "The NLRP3 inflammasome is a key mediator of inflammatory diseases, including atherosclerosis and other vascular diseases." (PMID 37109221, 2023). "NLRP3 has been best characterized for its role in atherosclerosis initiation and progression through its role in promoting vascular inflammation." (PMID 37443800, 2023). "This study firstly proves that oridonin prevents atherosclerosis progression by suppressing NLRP3 inflammasome activation and promoting Nrf2 antioxidative stress." (PMID 37155118, 2023). "In the peculiar context of atherosclerosis, shear stress on the endothelial wall, cholesterol crystals, and Ox-PL seem to be the primers of NLRP3 activation." (PMID 36983163, 2023). "The involvement of innate immunity in atherosclerosis is characterized by the activation of the NLRP3 inflammosome." (PMID 37446157, 2023).